TMEM151A (transmembrane protein 151A)
Synonyms: TMEM151; MGC33486; DYT36; EKD3
Tractability: Antibody: UniProt predicts a signal peptide or a membrane-spanning region.
Gene: Protein-coding gene on chromosome 11 (66,291,894 to 66,296,664, forward strand). Ensembl gene ENSG00000179292.
Subcellular location: Endoplasmic reticulum membrane; Cell projection, axon; Cell projection, dendrite; Cell membrane; Endosome membrane
Subcellular location (Human Protein Atlas): Nucleoli; Cytosol
Gene Ontology:
Cellular component: endoplasmic reticulum; endoplasmic reticulum membrane; endosome membrane; membrane; plasma membrane; axon; dendrite
Genetic constraint (gnomAD): Loss-of-function variants: 21 observed, 22.87 expected, observed/expected ratio (o/e) 0.92, 90% interval 0.65 to 1.32. The synonymous counts are far from expectation, so gnomAD's model fits this gene poorly and the ratio says little. Missense variants: 704 observed, 573.84 expected, observed/expected ratio (o/e) 1.23, 90% interval 1.15 to 1.31. Synonymous variants: 374 observed, 268.82 expected, observed/expected ratio (o/e) 1.39, 90% interval 1.28 to 1.52.
Homologues: Orthologues: chimpanzee TMEM151A (100% identical), macaque TMEM151A (99% identical), pig TMEM151A (99% identical), dog TMEM151A (98% identical), guinea pig TMEM151A (98% identical), mouse Tmem151a (97% identical), rat Tmem151a (97% identical), zebrafish TMEM151A (58% identical), zebrafish tmem151a (55% identical), Caenorhabditis elegans ZK1067.4 (34% identical). Paralogues in human: TMEM151B (56% identical).
Diseases named in the same sentence as TMEM151A in open-access papers:
TMEM151A is named in the same sentence as 7 diseases in open-access papers, as found by Europe PMC text mining. Sharing a sentence is not in itself a finding about the gene and the disease. The quoted sentences say what the papers report.
asthma (1 paper, 2023). "We screened seven candidate diagnostic biomarkers for asthma using LASSO regression (namely, BCL10, CD300E, IER2, MMP13, OAF, TBC1D3, and TMEM151A), among which the area under the curve (AUC) value for CD300E and IER2 were 0.722 and 0.856, respectively." (PMID 37259023, 2023).
movement disorder (2 papers, 2022 to 2023). Neurological conditions resulting in abnormal voluntary or involuntary movement, which may impact the speed, fluency, quality and ease of movement. "Apart from the TMEM151A gene, we also found several pathogenic mutations in other genes associated with other movement diseases." (PMID 35707035, 2022). "To further explore the role of TMEM151A mutations in PKD and other movement disorders and broaden the clinical and genetic spectrum of TMEM151A mutations, we performed whole-exome sequencing (WES) in 181 patients with different movement disorders." (PMID 35707035, 2022). "No mutation of the TMEM151A gene was found in the other type of movement disorders." (PMID 35707035, 2022). "No mutation of TMEM151A gene was found in other movement disorders." (PMID 35707035, 2022).
TMEM151A also shares sentences with these, for which no sentence is quoted: Dystonia (2 papers); Paroxysmal Kinesigenic Dyskinesia (2); Chorea (1); myoclonus-dystonia syndrome (1); paroxysmal non-kinesigenic dyskinesia (1).